ZSCAN20 (zinc finger and SCAN domain containing 20)
Description:
May be involved in transcriptional regulation.
Synonyms: KOX29; ZNF31; ZNF360; ZFP-31
Tractability: PROTAC: ubiquitination databases record sites on it.
Gene: Protein-coding gene on chromosome 1 (33,472,597 to 33,501,643, forward strand). Ensembl gene ENSG00000121903.
Subcellular location: Nucleus
Subcellular location (Human Protein Atlas): Nucleoplasm
Gene Ontology:
Molecular function: protein binding; DNA-binding transcription factor activity, RNA polymerase II-specific; RNA polymerase II cis-regulatory region sequence-specific DNA binding
Biological process: regulation of transcription by RNA polymerase II
Cellular component: nucleus
Genetic constraint (gnomAD): Loss-of-function variants: 39 observed, 100.51 expected, observed/expected ratio (o/e) 0.39, 90% interval 0.3 to 0.51. The upper end of that interval is the gene's LOEUF score, 0.51, which puts it in group 2 of 6, group 1 being the genes least tolerant of losing a copy. Missense variants: 1,115 observed, 1,351 expected, observed/expected ratio (o/e) 0.83, 90% interval 0.79 to 0.87. Synonymous variants: 456 observed, 488.33 expected, observed/expected ratio (o/e) 0.93, 90% interval 0.86 to 1.01.
Homologues: Orthologues: chimpanzee ZSCAN20 (99% identical), macaque ZSCAN20 (96% identical), dog ZSCAN20 (86% identical), pig ZSCAN20 (83% identical), guinea pig ZSCAN20 (81% identical), rabbit ZSCAN20 (78% identical), mouse Zscan20 (76% identical), rat Zscan20 (74% identical). Paralogues in human: ZSCAN2 (28% identical), ZNF256 (21% identical), ZNF304 (21% identical), ZNF79 (20% identical), ZNF480 (20% identical), ZNF583 (20% identical), ZNF551 (20% identical), ZNF570 (19% identical), ZNF587B (19% identical), ZNF792 (19% identical), ZNF549 (18% identical), ZNF418 (18% identical), and 26 more.
Diseases named in the same sentence as ZSCAN20 in open-access papers:
ZSCAN20 is named in the same sentence as 8 diseases in open-access papers, as found by Europe PMC text mining. Sharing a sentence is not in itself a finding about the gene and the disease. The quoted sentences say what the papers report.
glioma (3 papers, 2019 to 2023). A benign or malignant brain and spinal cord tumor that arises from glial cells (astrocytes, oligodendrocytes, ependymal cells). "These genes are all associated with glioma prognosis and ZSCAN20 is related to the immune infiltration of tumors." (PMID 36762114, 2023). "The article reports that ZSCAN20 is highly expressed in low-grade gliomas and can be used as a part of the model to predict the prognosis of low-grade gliomas." (PMID 36462500, 2022).
tumor (3 papers, 2022 to 2025). "We found that ZSCAN20 expression level was remarkably associated with 25 of the 26 T cell markers in LIHC after adjusting for tumor purity." (PMID 36462500, 2022). "The results indicated the high expression of ZSCAN20 was obviously associated with grade, stage and tumor size." (PMID 36462500, 2022). "The expression of ZSCAN20 had a considerable positive correlation with the levels of most markers in distinguished kinds of LIHC immune cells after regulating tumor purity." (PMID 36462500, 2022). "Initially, we used the TCGA, TIMER and ICGC databases to assess the difference between ZSCAN20 expression in specific tumor types." (PMID 36462500, 2022). "Subsequently, compared with adjacent normal samples, the expression of ZSCAN20 in 58 pairs of LIHC tumor samples was significantly increased." (PMID 36462500, 2022). "At the same time, it was worth noting that the ZSCAN20 promoter methylation profile based on gender, age, cancer stage, tumor grade and nodal metastasis status showed significant differences (all P < 0.01)." (PMID 36462500, 2022). "In order to understand the relationship between ZSCAN20 expression and tumor infiltrating immune cells, accordingly, we appraised the nexus between ZSCAN20 and a variety of immune cells." (PMID 36462500, 2022). "All results show that ZSCAN20 expression has a close connection with clinicopathological factors such as tumor progression and metastasis." (PMID 36462500, 2022). "The difference between ZSCAN20 expression in tumor and normal tissues was detected." (PMID 36462500, 2022). "In addition, we also used HPA database to detect that ZSCAN20 protein expression in tumor tissues was remarkably higher than normal tissues in the liver of patients with HCC." (PMID 36462500, 2022). "We found ZSCAN20 expression was extremely related to tumor purity." (PMID 36462500, 2022). "Furthermore, recent studies have found that ZSCAN20 may become a new target for tumor treatment." (PMID 36462500, 2022). "For the aim of examine the expression level of ZSCAN20 in HCC tissues, we performed IHC staining and examined 40 pairs tumor tissues of paraffin embedded archived HCC and corresponding 40 pairs paracancerous tissues." (PMID 36462500, 2022). "The results showed that ZSCAN20 expressed significantly different in various HCC samples, gender, age, cancer stages, tumor grade, nodal metastasis status, histological subtypes." (PMID 36462500, 2022).
cancer (2 papers, 2022 to 2024). A tumor composed of atypical neoplastic, often pleomorphic cells that invade other tissues. "We still need to further study whether ZSCAN20 affected the occurrence and development of cancer over Wnt signaling pathway in the cell cycle mechanism." (PMID 36462500, 2022). "There are few studies on ZSCAN20, and the mechanism of ZSCAN20’s role in cancer has not yet been elucidated." (PMID 36462500, 2022).
ZSCAN20 also shares sentences with these, for which no sentence is quoted: hepatocellular carcinoma (4 papers); angiosarcoma (1); breast carcinoma (1); Diabetes (1); myeloid neoplasm (1).